SLC30A1 (solute carrier family 30 member 1)
Description:
Zinc ion:proton antiporter that could function at the plasma membrane mediating zinc efflux from cells against its electrochemical gradient protecting them from intracellular zinc accumulation and toxicity. Alternatively, could prevent the transport to the plasma membrane of CACNB2, the L-type calcium channels regulatory subunit, through a yet to be defined mechanism. By modulating the expression of these channels at the plasma membrane, could prevent calcium and zinc influx into cells. By the same mechanism, could also prevent L-type calcium channels-mediated heavy metal influx into cells (By similarity). In some cells, could also function as a zinc ion:proton antiporter mediating zinc entry into the lumen of cytoplasmic vesicles. In macrophages, can increase zinc ions concentration into the lumen of cytoplasmic vesicles containing engulfed bacteria and could help inactivate them. Forms a complex with TMC6/EVER1 and TMC8/EVER2 at the ER membrane of keratynocytes which facilitates zinc uptake into the ER. Down-regulates the activity of transcription factors induced by zinc and cytokines. Also functions as a copper transporter, facilitating the entry of copper into cells, which is crucial for copper-induced cell death (cuproptosis). Acts as a Zn(2+)/Ca(2+) exchanger, exporting zinc in exchange for calcium influx.
Synonyms: ZNT1; ZRC1
Tractability: Small molecule: a structure with a bound ligand is known. Antibody: UniProt places it where antibodies can reach, with high confidence; its Gene Ontology location is reachable by antibodies, with high confidence; UniProt predicts a signal peptide or a membrane-spanning region; the Human Protein Atlas places it where antibodies can reach. PROTAC: ubiquitination databases record sites on it; its protein half-life has been measured.
Gene: Protein-coding gene on chromosome 1 (211,571,568 to 211,579,161, reverse strand). Ensembl gene ENSG00000170385.
Subcellular location: Cell membrane; Basolateral cell membrane; Cytoplasmic vesicle membrane; Cytoplasm; Endoplasmic reticulum membrane; Golgi apparatus membrane; Nucleus membrane; Postsynaptic density
Subcellular location (Human Protein Atlas): Plasma membrane; Vesicles
Pathways (Reactome):
Transport of small molecules: Zinc efflux and compartmentalization by the SLC30 family
Gene Ontology:
Molecular function: calcium:monoatomic cation antiporter activity; protein binding; zinc:proton antiporter activity; calcium channel inhibitor activity; zinc ion transmembrane transporter activity; monoatomic cation transmembrane transporter activity
Biological process: copper ion transport; defense response to bacterium; intracellular zinc ion homeostasis; zinc ion import into organelle; zinc ion transport; cadmium ion transmembrane transport; detoxification of zinc ion; intracellular calcium ion homeostasis; negative regulation of calcium ion import; negative regulation of neurotransmitter secretion; negative regulation of zinc ion transmembrane import; zinc export across plasma membrane; zinc ion transmembrane transport; calcium ion import; calcium ion transmembrane transport; detoxification of cadmium ion; monoatomic cation transport; positive regulation of dendritic spine morphogenesis; regulation of postsynaptic density protein 95 clustering; transmembrane transport
Cellular component: basolateral plasma membrane; cytoplasm; cytoplasmic vesicle membrane; endoplasmic reticulum; endoplasmic reticulum membrane; Golgi apparatus; Golgi membrane; nuclear membrane; plasma membrane; transmembrane transporter complex; membrane; T-tubule; cytoplasmic vesicle; dendrite; glutamatergic postsynaptic density; postsynaptic density; postsynaptic density membrane; postsynaptic density, intracellular component; Schaffer collateral - CA1 synapse; vesicle membrane
Genetic constraint (gnomAD): Loss-of-function variants: 6 observed, 28.92 expected, observed/expected ratio (o/e) 0.21, 90% interval 0.11 to 0.41. The upper end of that interval is the gene's LOEUF score, 0.41, which puts it in group 1 of 6, group 1 being the genes least tolerant of losing a copy. Missense variants: 434 observed, 672.43 expected, observed/expected ratio (o/e) 0.65, 90% interval 0.6 to 0.7. Synonymous variants: 253 observed, 259 expected, observed/expected ratio (o/e) 0.98, 90% interval 0.88 to 1.08.
Homologues: Orthologues: chimpanzee SLC30A1 (99% identical), macaque SLC30A1 (98% identical), pig SLC30A1 (91% identical), dog SLC30A1 (89% identical), rat Slc30a1 (86% identical), mouse Slc30a1 (85% identical), guinea pig SLC30A1 (74% identical), zebrafish slc30a1a (59% identical), tropical clawed frog slc30a1 (58% identical), rabbit SLC30A1 (56% identical), zebrafish slc30a1b (51% identical). Paralogues in human: SLC30A10 (33% identical), SLC30A5 (19% identical), SLC30A2 (19% identical), SLC30A3 (18% identical), SLC30A7 (18% identical), SLC30A8 (17% identical), SLC30A4 (16% identical), SLC30A6 (13% identical).
Diseases named in the same sentence as SLC30A1 in open-access papers:
SLC30A1 is named in the same sentence as 65 diseases in open-access papers, as found by Europe PMC text mining. Sharing a sentence is not in itself a finding about the gene and the disease. The quoted sentences say what the papers report.
prostate carcinoma (6 papers, 2019 to 2024). A carcinoma that arises from epithelial cells of the prostate gland. "Based on the Oncomine database records, the expression of Zn-exporter genes SLC30A1, SLC30A9, and SLC30A10 are upregulated, and SLC30A5 and SLC30A6 are downregulated in prostate cancer compared to BPH." (PMID 36551962, 2022). "SLC30A1 expression was increased and SLC39A8 decreased in MAC-MT cells in cancer compared to non-tumor samples, the overall effect of which may be to increase zinc efflux, potentially counteracting the known decreased zinc concentration associated with prostate cancer." (PMID 34936871, 2021). "We found that in prostate cancer, MAC-MT markedly increased the expression of the zinc efflux transporter SLC30A1, which may represent a mechanism to counteract the disrupted zinc transport present in tumor luminal epithelial cells." (PMID 34936871, 2021).
bladder cancer (4 papers, 2019 to 2022). "SLC30A1 is upregulated in bladder cancer and negatively targeted by miR-411 to inhibit the growth and metastasis of bladder cancer cells." (PMID 33110097, 2020). "In addition, miRNA-411 can potentially modulate the malignant biological behavior of bladder cancer cells by targeting and regulating SLC30A1 expression." (PMID 35154468, 2022). "This may reveal new insight as to the role of cadmium in (bladder) cancer, where previously reported SLC30A1 and MT changes may reflect increased concentrations of intracellular cadmium rather than zinc." (PMID 30884885, 2019).
breast carcinoma (4 papers, 2021 to 2026). "In further investigations, four breast cancer cell lines were screened for mRNA expression of MT1F, MT1E, SLC30A1, and S100P after treatment with BA or CAI3 and showed an upregulation of MT1F, MT1E, SLC30A1, and S100P in four breast cancer cell lines." (PMID 39594441, 2024).
depression (4 papers, 2015 to 2023). "Depression of plasma miR-182 and miR-185 in subjects exposed to high levels of PM2.5 and overexpression of SLC30A1, SERPINB2 and AKR1C1 in human lung cancer tissues were detected." (PMID 26338969, 2015).
gastric cancer (4 papers, 2019 to 2023). A primary or metastatic malignant neoplasm involving the stomach. "For SLC30A1, a proton-coupled zinc antiporter, its upregulation is found in gastric cancer and cervical carcinoma." (PMID 37295717, 2023). "We found that the median expression levels of SLC30A1-3, 5–7, and 9 were significantly upregulated in gastric cancer tissues compared to non-cancerous tissues, while SLC30A4 was downregulated." (PMID 33110097, 2020). "In the present study, mRNA expression of SLC30A1-3, SLC30A5-7, and 9 was significantly upregulated in gastric cancer tissues compared to non-cancer tissues in GC patients, while SLC30A4 was downregulated in cancer tissues." (PMID 33110097, 2020).
lung carcinoma (3 papers, 2015 to 2022). "The analysis of SLC30A1, SERPINB2 and AKR1C1 levels in human lung specimens from the TCGA database also revealed the aberrant expression of these genes in lung cancer tissues compared with paired normal tissues." (PMID 26338969, 2015). "We further analyzed SLC30A1, SERPINB2 and AKR1C1 mRNA expressions in human lung cancer retrieved from the TCGA database." (PMID 26338969, 2015). "Increased expressions of SLC30A1, SERPINB2 and AKR1C1 were detected in human lung cancer." (PMID 26338969, 2015). "Although these results did not provide direct evidence that the aberrant expression of SLC30A1, SERPINB2 and AKR1C1 in human lung cancer is caused by exposure to PM2.5, they did indicate a role in the development of lung cancer of these genes whose expression can be induced by PM2.5 organic extract." (PMID 26338969, 2015).
ovarian carcinoma (3 papers, 2019 to 2022). A malignant neoplasm originating from the surface ovarian epithelium. "In addition, upregulation of SLC30A1 expression in ovarian cancer cells counteracted the apoptotic effects of microRNA-8073 mimics on SKOV3 and OVCAR3 cells, indicating that SLC30A1 has anti-apoptotic effects." (PMID 35154468, 2022). "Meanwhile, SLC30A1 has high expression in ovarian cancer (OC) cell lines and tissues and a recovery experiment revealed that upregulated SLC30A1 counteracts the effect of miR-8073 mimics on OC cell proliferation and apoptosis to affect the malignant progression of OC50." (PMID 33110097, 2020).
cervical carcinoma (2 papers, 2022 to 2023). A carcinoma arising from either the exocervical squamous epithelium or the endocervical glandular epithelium. "To identify cancer-related signaling pathways associated with SLC30A1/10 in cervical cancer, we performed GSEA analysis." (PMID 35154468, 2022). "Then, in order to identify cancer-related signaling pathways associated with SLC30A1/10 genes in cervical cancer, we performed GSEA analysis according to SLC30A1/10 gene expression." (PMID 35154468, 2022). "And a high expression of SLC30A1, SLC30A6, SLC30A8 and SLC30A10 was associated with worse overall survival in cervical carcinoma patients." (PMID 35154468, 2022). "In other words, our study was the first one to investigate the roles of SLC30A1-10 genes in cervical carcinoma." (PMID 35154468, 2022). "To elucidate the potential molecular mechanisms of SLC30s in cervical carcinoma, we constructed a regulatory network between SLC30A1-10 using the STRING tool and GeneMANIA tool, respectively." (PMID 35154468, 2022). "Additionally, ROC curves were performed to evaluate the diagnostic effects of SLC30A1 and SLC30A10 in cervical carcinoma." (PMID 35154468, 2022). "Therefore, SLC30A1 and SLC30A10 can be used as potential diagnostic indicators and therapeutic targets in cervical carcinoma." (PMID 35154468, 2022). "Therefore, the correlation of SLC30A1/10 expression with immune markers was investigated in cervical cancer using the TISIDB platform." (PMID 35154468, 2022). "Besides, we found that SLC30A1/10 may have a potential regulatory role in immune infiltration in cervical carcinoma." (PMID 35154468, 2022). "Besides, to further demonstrate that whether SLC30A1/10 in cervical carcinoma may have a potential regulatory role in immune infiltration, we analyzed the relationship between SLC30A1/10 and immune infiltrating cells." (PMID 35154468, 2022). "However, after comprehensive integrative analyses of SLC30A1-10 genes in cervical carcinoma, we found that only two genes, SLC30A1 and SLC30A10, may potentially play a pro-cancerous role in cervical cancer." (PMID 35154468, 2022). "For metastases, we found that SLC30A1, SLC30A7 and SLC30A10 expression were positively correlated with lymph node metastasis or distant metastasis in cervical carcinoma." (PMID 35154468, 2022). "Data in the UALCAN tool revealed that mRNA expressions of SLC30A1, SLC30A7 and SLC30A10 were significantly higher in cervical cancer tissues, while SLC30A2 and SLC30A8 mRNA levels were decreased compared to normal tissues." (PMID 35154468, 2022). "And we investigated the expression of SLC30A1 and SLC30A10 in cervical carcinoma by performing immunohistochemical staining on 31 pairs of tissues." (PMID 35154468, 2022). "And we validated the expression of SLC30A1 and SLC30A10 in cervical carcinoma by performing immunohistochemical staining on 31 pairs of tissues." (PMID 35154468, 2022). "The results showed that the expression of SLC30A1 and SLC30A10 was elevated in cervical carcinoma tissues compared with paracancerous tissues." (PMID 35154468, 2022). "Besides, we found that SLC30A1, SLC30A7 and SLC30A10 expression was positively correlated with lymph node metastasis or distant metastasis in cervical carcinoma." (PMID 35154468, 2022). "In conclusion, we identified two genes (SLC30A1 and SLC30A10) that may play a promotional role in cervical cancer." (PMID 35154468, 2022). "Therefore, the correlation of SLC30A1 and SLC30A10 expression with immune cells and biomarkers in cervical cancer were investigated using the TISIDB platform." (PMID 35154468, 2022). "SLC30A1 and SLC30A10 can effectively distinguish cervical carcinoma patients, respectively." (PMID 35154468, 2022). "For immunostimulator, SLC30A1 expression positively correlated with IL6R (Spearman: ρ = 0.204, P = 0.000345), TNFSF15 (Spearman: ρ = 0.355, P = 2.19e-10), NT5E (Spearman: ρ = 0.299, P = 1.16e-07), and PVR (Spearman: ρ = 0.236, P = 3.29e-05) in cervical carcinoma." (PMID 35154468, 2022).
cervical carcinoma (continued). "For tumor stages, SLC30A1, SLC30A7 and SLC30A10 groups significantly varied, whereas SLC30A2, SLC30A3, SLC30A4, SLC30A5, SLC30A6, SLC30A8 and SLC30A9 did not significantly differ in cervical carcinoma." (PMID 35154468, 2022).
gastric adenocarcinoma (2 papers, 2019 to 2023). "In addition, we found that the expression levels of SLC30A1, SLC30A5, SLC30A6 and SLC30A7 were significantly elevated, while the expression level of SLC30A4 was significantly decreased in gastric adenocarcinoma tissues compared with both normal gastric tissues and matched normal gastric tissues." (PMID 37524874, 2023).
viral infection (2 papers, 2019 to 2022). "Both genes identified, SLC30A1 and SLC35A1, represent novel host factors that affected the induction of apoptosis upon viral infection." (PMID 31320712, 2019).
chronic myeloid leukemia (1 paper, 2025). "Recently, a genome-wide CRISPR/Cas9 screen in the human chronic myeloid leukemia cell line K562 identified ABCC1, SLC30A1, and AQP3 as important regulators of arsenic toxicity." (PMID 39578074, 2025).
diabetic neuropathy (1 paper, 2025). A chronic, pathological complication associated with diabetes mellitus, where nerve damages are incurred due to diabetic microvascular injury involving small blood vessels that supply these nerves, resulting in peripheral and/or autonomic nerve dysfunction. "In addition, further research is needed to explore the roles of specific biomolecules implicated in diabetic neuropathy development, such as SLC30A1, TRBJ2‐7, OLFM1, TCF7L2, MCF2L, CEP295NL, CEACAM22P, TSHZ2, and PDZD4." (PMID 40692573, 2025).
dilated cardiomyopathy (1 paper, 2019). Cardiomyopathy which is characterized by dilation and contractile dysfunction of the left and right ventricles. "Of note, several iPTGs, such as ACTA2, FHL2, PARD6B, and SLC30A1, may be linked to iASPP-related phenotypes such as sudden cardiac death and dilated cardiomyopathy." (PMID 31395738, 2019).
fibrosarcoma (1 paper, 2015). A malignant mesenchymal fibroblastic neoplasm affecting the soft tissue and bone. "Following subcutaneous injection of these cells into nude mice, fibrosarcoma were formed from SLC30A1- or SERPINB2-expressing cells." (PMID 26338969, 2015).
Salmonella Infections (1 paper, 2024). Infections with bacteria of the genus SALMONELLA. "(G) Model showing the predicted effects of the loss of Slc30a1 on cellular zinc trafficking and intracellular zinc accumulation in BMDMs in response to Salmonella infection." (PMID 39475776, 2024). "Lyz2-Cre-driven Slc30a1 conditional knockout mice (Slc30a1fl/fl;Lyz2-Cre) exhibit increased susceptibility to Salmonella infection compared to control littermates." (PMID 39475776, 2024). "Lyz2-Cre-driven Slc30a1 conditional knockout mice are highly susceptible to Salmonella infection." (PMID 39475776, 2024). "Based on these results, we hypothesize that the loss of Slc30a1 leads to an abnormal increase in intracellular zinc during Salmonella infection and increases the expression of Mt1, possibly to compensate for the excessive intracellular zinc by increasing Mt1-mediated zinc storage." (PMID 39475776, 2024). "Slc30a1 is required for iNOS/nitric oxide (NO) production and intracellular pathogen-killing capacity of macrophages in response to Salmonella infection." (PMID 39475776, 2024). "In conclusion, we report that Slc30a1 of macrophages plays a protective role against Salmonella infection by regulating iNOS and NO activities, which are essential for bacterial clearance through NF-κB signaling." (PMID 39475776, 2024). "Here, we provide the first in vivo evidence that Slc30a1 in macrophages plays a key role in host protection against Salmonella infection." (PMID 39475776, 2024). "Lastly, we used primary macrophages differentiated from the bone marrow of Slc30a1 cKO mice to directly investigate the killing capacity and the antimicrobial response of macrophages to Salmonella infection." (PMID 39475776, 2024). "To study the role of Slc30a1 in macrophages, we generate Slc30a1fl/fl;Lyz2-Cre (Slc30a1 cKO) mice and induce Salmonella infection." (PMID 39475776, 2024). "Bulk transcriptome sequencing in primary macrophages identifies Slc30a1 as a candidate in response to Salmonella infection." (PMID 39475776, 2024). "Induction of Slc30a1 expression in macrophages of a Slc30a1 reporter mouse upon Salmonella infection." (PMID 39475776, 2024). "An interesting finding from our in vivo experiments is that our Lyz2-Cre-driven Slc30a1 conditional knockout mice fail to redistribute zinc levels in the serum and spleen following Salmonella infection." (PMID 39475776, 2024). "Together, these data show that Slc30a1 is upregulated in macrophages during Salmonella infection." (PMID 39475776, 2024). "Together, these in vivo data provide compelling evidence that Slc30a1 in macrophages may play an important protective role against Salmonella infection." (PMID 39475776, 2024). "To detect the levels of Slc30a1 protein in macrophages following Salmonella infection, we generated a Slc30a1 reporter mouse line expressing 3xFlag-2A-EGFP-2A-CreERT2-Wpre-pA under the control of the Slc30a1 promoter and studied heterozygous offspring mice (Slc30a1flag-EGFP/+)." (PMID 39475776, 2024). "We show that mice lacking Slc30a1 in macrophages are highly susceptible to Salmonella infection." (PMID 39475776, 2024). "We found that 30 min after Salmonella infection (MOI = 1), FluoZin-3 fluorescence was significantly higher in Slc30a1 cKO cells; similar results were obtained when the cells were exposed to H2O2 (1 mM), LPS (1 μg/ml), or HK-ST (MOI = 100)." (PMID 39475776, 2024). "Interestingly, however, the Slc30a1-flag reporter was present both in the cytosol and in the plasma membrane in Salmonella-infected cells, suggesting that Slc30a1 may contribute to both zinc efflux and intracellular zinc movement in response to Salmonella infection." (PMID 39475776, 2024).
squamous cell carcinoma (1 paper, 2015). A carcinoma arising from squamous epithelial cells. "It was found that the median SLC30A1 RNA level in lung tumor tissues was significantly higher than that in normal tissues (8.459 versus 7.837, P < 0.0001); however, this significant difference was only occurred in adenocarcinoma but not in squamous cell carcinoma." (PMID 26338969, 2015).